FOXP3 (forkhead box P3)
Diseases named in the same sentence as FOXP3 in open-access papers (continued):
Sharing a sentence is not in itself a finding about the gene and the disease.
tumor (continued). "It has been previously demonstrated that the TP63/TP53L, ERG, GRHL1/Get-, HNF1A/TCF-1, SPI1/PU.1, WT1 and GLIS2, FOXM1 and FOXP3 transcription factor networks, which are mediated by HNF4A, can regulate the expression of Trop2 in tumor tissues." (PMID 25779928, 2015). "One possible explanation to this phenomenon is a relative scarcity of tumor-reactive T-cells in extra-pulmonary lesions as compared to lung, as would be represented by a low CD8:Foxp3 ratio." (PMID 26317902, 2015). "It is of note, however, that tumor microenvironment including elevated CD8+ T cells, forkhead box protein 3 (FoxP3)+ T cells, and CD68+ macrophages can also contribute to the downgrading of bone marrow FL." (PMID 25815348, 2015). "The data of these cells in NSCLC are relatively rare and controversial therefore we aimed to evaluate the infiltration patterns of Foxp3+CD4+, CD4+ and CD8+ T cells in tumor islets and stroma from patients with NSCLC and to analyze their relations to survival." (PMID 26604855, 2015). "Conversely, CD4+ forkhead box P3 (FOXP3+), CD4+ Th2 cells, M2 macrophages, and myeloid-derived suppressor cells (MDSCs) promote tumor growth." (PMID 26300242, 2015). "In the case of the Foxp3− CD4+ T-cell population, the tumour-infiltrating T-cell population is far more heterogeneous." (PMID 25495686, 2015). "FoxP3 and CTLA-4 are expressed in about 20% of CD25high cells among PBMCs and about 30% of the CD25+ cells infiltrating the tumours, resulting in an increase of about 1.5-fold in TILs." (PMID 25961057, 2015). "Moreover, the stratified analysis suggested the molecular subtype or tumor stage influenced the prognostic value of FoxP3+ Tregs in certain types of cancer, but the prognostic variability may not be attributable to different scoring strategies, follow-up duration, multivariate corrected or not." (PMID 26462617, 2015). "Some studies showed that the ratio between tumor infiltrating CD8+T cells and Foxp3+CD4+ T cells gives prognostic/predictive information than either parameter alone." (PMID 26604855, 2015). "The Foxp3-expressing cancer cells inhibited the proliferation of CD4+CD25− T cells, potentially contributing to immune evasion of the tumor cells." (PMID 24932293, 2014). "Since CD4+CD25+ T cells expressing Foxp3 (regulatory T cells) have been related to the progression of SCC, the presence of these cells in the tumor was evaluated." (PMID 25268644, 2014). "An accumulation of CD8+ T cells, including tumor- and herpes simplex virus type-1-specific populations, and a decrease in the number of CD4+ Foxp3+ T regulatory cells were seen in both HF10- and DTA-1-treated tumors." (PMID 25105508, 2014). "In tumor-infiltrating lymphocyte (TIL) population, the percentage of CD4+Foxp3+LAP+ T cells correlated with that of CD4+Foxp3+ T cells (r2 = 0.1, P = 0.04)." (PMID 25268580, 2014). "Based on the ratios of the stimulatory-to-regulatory gene transcripts (ratios of both T-bet/FoxP3 and IFN-γ/IL-10), we concluded that combined treatment fostered a local immuno-activating tumor microenvironment." (PMID 24586709, 2014). "Foxp3+CD25+CD4+ T regulatory cells (Tregs), with immunosuppressive activity against tumor-specific T cell responses, are one of the crucial players for immune tolerance." (PMID 24761979, 2014). "FoxP3+CD25HiCD4+ regulatory T cells, which express high levels of the CCL22 receptor CCR4, also infiltrate tumour sites where they expand in response to TNF and IL-2 produced by effector T cells, and subsequently inhibit the immune response." (PMID 24957270, 2014). "In this setting, we observed that single PD-1 blockade had little effects on tumor-resident CD4+ and CD8+ T cells while slightly diminishing the levels of immunosuppressive CD4+FoxP3+ Treg and CD11b+GR-1+ MDSC in peritoneal cavity." (PMID 24586709, 2014).
tumor (continued). "In order to assess whether Foxp3 expression was specific for macrophages from Renca tumors, we performed flow cytometric analysis on macrophages and other cell subsets from normal kidney, bone marrow (BM) and spleen harvested from naïve mice and IK tumor-bearing mice." (PMID 25264896, 2014). "As soon as FoxP3+ cells outweigh CD8+ cells, they will infiltrate into the tumor and spread throughout the specimen." (PMID 25365237, 2014). "CD4(+) T-cell frequency correlated with tumor size, FoxP3(+) regulatory T-cell (Treg) frequency correlated with lymph node metastasis, and CD8 to Treg ratio inversely correlated with tumor size." (PMID 25328756, 2014). "Overexpression of FOXP3 and CTLA4 in total BM samples suggests a local accumulation of immunosuppressive Tregs, the MM tumor environment, possibly dampening anti-tumor host immune responses." (PMID 25099367, 2014). "This implicates regulation of the balance between CD4+CD25+Foxp3+Treg and CD4+IL-17+ Th17 as a new strategy to reverse tumor progression." (PMID 24949077, 2014). "We also searched for FoxP3-positive regulatory T-cells (Tregs), since IDO-1 has been reported to increase the proportion of Tregs in the tumor infiltrate." (PMID 25928531, 2014). "High expression of FoxP3, vimentin and L1CAM in PDAC cells as well as a tumor-related localization of macrophages each tended to correlate with higher tumor grade." (PMID 24797069, 2014). "Regulatory CD4+FoxP3+ and suppressor CD8+FoxP3+ T cells and myeloid-derived suppressor cells were evaluated in injected tumor biopsies and found to be decreased when compared to unvaccinated control patients." (PMID 24971166, 2014). "In addition, high levels of CD3 but low levels of FoxP3 and L1CAM in tumor cells tended to correlate with improved patient survival, being in line with previous reports demonstrating high tumor-associated expression of FoxP3 and L1CAM as negative prognostic marker." (PMID 24797069, 2014). "After 5 days in mixed tumor-lymphocyte cultures (MTLC), T cells were assayed for the acquisition of FoxP3 expression and for cytokine production at the single-cell level." (PMID 24903009, 2014). "In accordance with prior murine and human studies, we confirmed the presence of FOXP3+ Treg in PDA tumors and made the new observation that they are markedly enriched in the tumor microenvironment relative to the blood." (PMID 24794217, 2014). "When the proliferation of tumor cells was inhibited by CTX and THP, the expression of Foxp3 also significantly decreased." (PMID 24932293, 2014). "Third, we only detected Foxp3+ and CD8+ cells but as there existed complicated interactions among various immune cells in tumor microenvironment, it would be more reasonable to include all TIL subsets in multivariate models." (PMID 24276989, 2014). "NAC (ACT, ACTCap) significantly reduced Tregs (% FOXP3+, AbN CTLA-4+), but only after 8 cycles and following a complete or substantial reduction in tumour mass." (PMID 23320561, 2013). "The depletion of Foxp3+ T cells and disruption of VEGF production on tumor cells mimic the phenotype seen in CD4+ T-cell specific Nrp1-deficient mice." (PMID 24324469, 2013). "We demonstrate for the first time that FOXP3-specific T cells can effectively lyse a basal type, triple negative cell line SUM149 derived from IBC patient tumor." (PMID 23341929, 2013). "In parallel, tumour infiltration by CD4, CD8 and Foxp3 regulatory T cells was evaluated by immunohistochemistry and correlated with TCR-sequencing data." (PMID 24122851, 2013). "Thus, although the effect of FOXP3 onactivated T cellsmay down-regulate some of theireffector functions, its expression could identify two distinct subsets of tumor infiltrating lymphocytes with opposite effects on tumor outcome." (PMID 23977174, 2013).
tumor (continued). "We propose that effector CD4+ T cells, which are largely regulated by Foxp3+ Tregs during tumor formation, are capable of maintaining immune control against FBL-3 tumor via direct killing and can functionally replace CD8+ T cells." (PMID 22890822, 2013). "Higher frequencies of Foxp3+CD4+ T cells are however also observed in spleen/blood and draining lymph of tumor-bearing mice and patients with cancer compared to non-tumor-bearing controls." (PMID 23874342, 2013). "An increase in Foxp3 and CD25 expression was observed in a time-dependent manner during tumor growth at 7, 14 and 21 days." (PMID 24179494, 2013). "In 10 patients with available matched tumor specimen and peripheral blood samples, significantly higher percentage of CD4 + FOXP3+ T-regulatory cells and lower ratio of CD8+/CD4 + FOXP3+ in the tumor compared with blood were reported." (PMID 24499550, 2013). "Tumor infiltrating cells were analyzed by flow cytometry following staining with antibodies to CD8, CD4, and FoxP3." (PMID 23935927, 2013). "The majority of tumor-derived Tim-3+ CD4 T cells exhibited an impaired capacity to produce IFN-γ and IL-2, but expressed higher levels of CD25, Foxp3, CTLA-4 and GITR than their Tim-3− CD4 T cell counterparts." (PMID 23526963, 2013). "The present study reveals phosphorylation of FOXP3 by LCK, a Src family kinase that modulates tumor progression." (PMID 24155921, 2013). "The analysis on the T-cell tumor infiltrates showed an increase of CD4+granzyme+ T-cells and a decreased number of CD4+CD25+Foxp3+ Treg elements from mice treated with either gp10025-33 peptide-pulsed DC vaccination or anti-IL-10 mAb administration." (PMID 23663506, 2013). "Activated tumor-infiltrating Tregs were found to express higher levels of CTLA-4, GITR and PD-1, which were observed in the Tim-3+Foxp3+ CD4 T cells." (PMID 23526963, 2013). "For instance, human tumor-infiltrating CD8+/CD28- regulatory T cells secrete IL-10, TNF-α, and IFN-γ, express FOXP3, and suppress the proliferation of CD8+ effector T cells." (PMID 23272178, 2012). "As most tumor-associated antigens are derived from a mutated form of self and since T-regs play a key role in maintaining self-tolerance, we analyzed whether or not vaccination with either full-length or epitope encoded Mam-A DNA induced higher numbers of T-regs (CD4+CD25+FoxP3+)." (PMID 22911764, 2012). "Tumor infiltrating immune cells such as CD4+, CD8+ and FOXP3+ T-cells and macrophages secrete soluble effector molecules such as interferons, IL-6 and TNF, and some of these can directly influence innate immune gene expression in keratinocytes." (PMID 22808251, 2012). "In contrast, increase tumor densities of Tregs, measured by surface markers CD4 and CD25 plus intracellular FoxP3, as compared to TM40D control, suggestive of a shift of the Treg population from the circulation to the primary tumor." (PMID 23029485, 2012). "The tumor microenvironment contains not only CD8+ T cells and memory effector cells, but also immunosuppressive cells such as FoxP3+ Tregs, myeloid-derived suppressor cells, tumor-associated macrophages, and cancer-associated fibroblasts." (PMID 24213505, 2012). "Only ∼10% of tumor-infiltrating FoxP3+ T cells were GFP− tdTomato+ cells, suggesting that only ∼1 out 10 FoxP3+ T cells in tumors lost the FoxP3 expression since their immigration into tumors or generation." (PMID 22292042, 2012). "CD4+FOXP3− cells from both unaffected colonic tissue and tumors had a lower demethylation than the CD4+FOXP3+ cells (range 51–100% and 53–74% in the tumor and unaffected tissue, respectively)." (PMID 22319577, 2012). "Foxp3+CD25+CD4+regulatory T (T reg) cells constitute about 5–10% of peripheral CD4+T cells and control immunological self-tolerance and tumor immunity." (PMID 21533081, 2011).
tumor (continued). "Our results showed that FoxP3+ Tregs highly aggregated and were in an activated phenotype (CD69+HLA-DRhigh) in the tumor site, where they can suppress the proliferation and INF-γ secretion of CD4+CD25− T cells." (PMID 21935436, 2011). "aAPC-expanded TILs undergo numerical expansion of tumor antigen-specific cells, remain amenable to secondary aAPC-based expansion, and have low CD4/CD8 ratios and FOXP3+ CD4+ cell frequencies." (PMID 21827675, 2011). "A recent study identified circulating and tumor-infiltrating CD28+CD8+ Tregs with a CD25+, FOXP3+, CD152+, GITR+, CD194+, TGF-β+, and CD127− phenotype." (PMID 22110523, 2011). "The improved anti-tumor immune response was accompanied by a transient decrease in the frequency and absolute number of CD4+CD25+FoxP3+ T cells (Tregs)." (PMID 21859450, 2011). "These "young" TILs are tumor-reactive, positively skewed in CD8+ lymphocyte composition, CD28 and CD27 expression, and contain fewer FOXP3+ T cells compared to parallel IL-2 cultures." (PMID 21827675, 2011). "Thus, FOXP3-expression and the associated regulatory phenotype might be an adverse biologic and clinical factor in rare PTCL cases that contributes to the aggressiveness of the tumor." (PMID 22151904, 2011). "FOXP3+ T-cell density of the SLN, primary tumour size, and Lauren classification were selected as significant predictors of non-SLN metastasis, including micrometastases and macrometastases, by this approach." (PMID 21730981, 2011). "FOXP3 expression in cutaneous and systemic CD30+ lymphoproliferations is generally confined to tumor infiltrating Tregs." (PMID 22151904, 2011). "A study has revealed that in parallel to high levels of CD4+Foxp3+ Treg cells, IL-17+ T cells including CD4+ T cells and CD8+ T cells were kinetically induced in the tumor microenvironment in multiple mouse and human tumors." (PMID 21943203, 2011). "In this study we investigated SPARC and FOXP3 in stage II and III CRC tissue and compare their prognostic value against the known CRC prognostic markers CD8 and CD45RO that are expressed by tumour infiltrating T lymphocytes." (PMID 21818290, 2011). "A recent study identified circulating and tumor infiltrating CD28+ CD8+ Tregs with a CD25+, FOXP3+, CTLA-4+, GITR+, CCR4+, TGF-β+ and CD127low/neg phenotype." (PMID 24212779, 2011). "We confirmed a significant enrichment of Foxp3-positive CD4 TIL and splenocytes in wild-type, B16 tumor-bearing C57BL/6 Foxp3EGFP mice." (PMID 22112546, 2011). "Recently, the prognostic value of various tumor-infiltrating CD4+ T-cell populations (CD4+CD25+, CD4+CD69+, and CD4+FOXP3+ T cells) was determined in HNSCC patients." (PMID 21437225, 2010). "Because the total number of cells was also increased two-fold in the lymph nodes of tumor-treated animals, the total increase in CD4+ CD25+ Foxp3+ was approximately four-fold, compared to the PBS-injected animals." (PMID 21170379, 2010). "We performed immunohistology on the tumor graft site, and sections were incubated with anti-CD4, anti-CD25, anti-FoxP3, and anti-GITR antibodies." (PMID 21170379, 2010). "Immunohistochemical quantification (score 0-3) was performed for CD3, CD4, CD8, CD45RO, CD68, CD163, FoxP3, GranzymeB, iNOS, mast cell tryptase, MUM1, PD1 and TIA-1 tumor-infiltrating (TILs) reactive cells." (PMID 21179245, 2010). "Changes in tumor growth, cell cytotoxic activity and populations of CD4+/FoxP3+ T regulatory cells (Treg) in the TSLN were evaluated." (PMID 20946663, 2010). "In contrast with the induction of Foxp3+ Treg cells in the periphery, there is evidence that in the tumor microenvironment, STAT3 signaling through IL-23R expression increases Foxp3 and IL-10 expression by Treg cells." (PMID 20732640, 2010). "In mice injected with tumor cells in TBHsp70 solution, staining for CD4, CD25, FoxP3 and GITR was observed in overlapping areas, mostly surrounding the tumor mass, as well as inside the tumor." (PMID 21170379, 2010).
tumor (continued). "In contrast, tumor size, lymphoid nodal status, TNM clinical stage and the density of Foxp3+TIL were predictors for OS and PFS." (PMID 20064222, 2010). "We also show that the numbers of tumour infiltrating CD3+ T-cells, CD8+ and GranzymeB+ cytotoxic T-cells as well as of FoxP3+ Treg are similar in primary HNSCC and in lymph node metastases." (PMID 19698134, 2009). "Tumour-infiltrating immune cells were identified using antibodies specific for CD3, CD8, GranzymeB, FoxP3, CD20 and CD68 and quantified using an image analysis system." (PMID 19698134, 2009). "Foxp3+ and CD3+ cells were detected in each tumor type, and the overall number of Foxp3+ and CD3+ cells was lower in K-RasLA2 mice than in mice treated with NNK." (PMID 19330036, 2009). "Specifically, the presence of NY-ESO-1-specific IgG autoantibodies in serum correlated with infiltration of tumor stroma by cells expressing CD8, CD4 and FoxP3." (PMID 18923710, 2008). "The comparison of MSI-H and MSS CRCs revealed a significantly higher number of intraepithelial FOXP3-positive lymphocytes in MSI-H compared with MSS CRCs and a trend towards a higher infiltration with these cells in the tumour stroma of MSI-H CRCs." (PMID 18985040, 2008). "Tumor tissue was examined by immunohistochemistry for expression of NY-ESO-1, various T cell markers (CD3, CD4, CD8, CD25, FoxP3, TIA-1 and Granzyme B) and other immunological markers (CD20, MHC class I and MHC class II)." (PMID 18923710, 2008). "We analyzed tumor and infectious disease antigen-specific CD8+ T-cell immune monitoring, FoxP3 mRNA quantitation, and T-cell activation/memory marker surface staining concurrently to detect trends relating to clinical parameters." (PMID 18452610, 2008). "Similar to CD3+ cells, CD8+, CD4+, FoxP3+ and TIA-1+ cells were generally denser in tumor stroma than tumor epithelium." (PMID 18923710, 2008). "A final consideration is that, in the present study, autoantibody responses to NY-ESO-1 were correlated with infiltration of tumor by not only CD8+ T cells, but also by CD4+ and FoxP3+ T cells." (PMID 18923710, 2008). "As observed for the FOXP3 stain, all tumours showed infiltration with CD3-positive and CD8-positive lymphocytes, which was higher in the tumour stroma than in the epithelium." (PMID 18985040, 2008). "We first found a significant enrichment of CD4+FOXP3+ Tregs in tumours developing in vivo, where approximately half of total CD4+ TIL were FOXP3+." (PMID 17565340, 2007). "High levels of FoxP3 and ILT3 expression were observed in more than 85% of the samples in each category, including the primary tumour, and were expressed at levels roughly equivalent to the housekeeping gene (HK=1.00)." (PMID 17565341, 2007). "Neutralize tumor TGF‐β; blocks de‐novo Treg conversion and FoxP3." (PMID 41537174, 2026). "Concerning the tumour bed stromal components, only morphometrical quantification highlighted the prognostic role of fibrosis and inflammation, particularly when distinguishing CD4+ and FOXP3+ cells, mainly in adenocarcinomas." (PMID 41207797, 2026). "Given FoxP3’s pivotal role in Treg function and its regulatory nexus with NAC1, we set out to investigate whether NAC1 has any impact on tumor growth." (PMID 39773913, 2025). "For instance, PDPN-expressing cancer-associated fibroblasts (PDPN+ CAFs) are associated with an immunosuppressive tumor microenvironment characterized by increased CD204+ tumor-associated macrophage infiltration, while CD8+ and FOXP3+ TILs did not." (PMID 41573582, 2025). "When the two drugs were administered concurrently, there were no consistent changes in the number and ratio of CD8+ T cells and FoxP3+ T cells within the tumor, nor did they exhibit positive synergistic immune effects." (PMID 41335282, 2025). "Additionally, adenoviruses can reshape the tumor microenvironment by recruiting CD45+ leukocytes and CD8+ lymphocytes while inhibiting FoxP3+ lymphocyte infiltration." (PMID 40070841, 2025).